IL10 (interleukin 10)
Diseases named in the same sentence as IL10 in open-access papers (continued):
Sharing a sentence is not in itself a finding about the gene and the disease.
tumor (continued). "Except for CXCR6, all cytokines/cytokine receptors were shown to operate in the spine, with CX3CL1, CX3CR1, IL10, CCL2, CXCL12, and CXCR4 mediating bone marrow colonization, CXCL5 and TGFβ promoting tumor cell proliferation, and TGFβ additionally driving bone remodeling." (PMID 36835198, 2023). "PD-L1, TGFB1, IL10, and IL13 are primary effectors for immunosuppressive tumor microenvironment." (PMID 36906597, 2023). "MDSC-derived IL-10 has been shown to inhibit IL-12 production and DC activation, and MDSC-derived fibroblast growth factor 1 has been shown to activate CAFs, resulting in tumor growth." (PMID 36773210, 2023). "Therefore, IL-10 therapy has great potential in reinvigorating CD8+ TEXs and boosting anti-tumor immunity." (PMID 37398660, 2023). "Tumor cells may release factors that suppress DC function, such as TGF-β and IL-10, or hinder their differentiation and maturation, such as VEGF, ultimately leading to the prevention of T cell activation and ineffective immune responses." (PMID 37345131, 2023). "In the positive‐ITGB1 expression group, IL‐10 expression was detected in 80.6% (25/31) of tumor cells, whereas in the negative‐ITGB1 expression group, only 28.6% (6/21) of tumor cells showed IL‐10 expression (p < 0.001)." (PMID 35864742, 2023). "The frequencies of immune cells (CD4+ T cells, CD8+ T cell, Treg cells, NK cells and CTLs) and the concentrations of cytokines (including IL-6, IL-12, Interferon (IFN)-γ, IL-10 and TGF-β) in tumour tissues were used to evaluate the immune status of the tumour microenvironment." (PMID 37076492, 2023). "However, TAMs have gene sets enriched in other GO terms involved in inflammatory resolution and tissue regeneration (e.g., positive regulation of IL‐10 and VEGF) and the glycolytic process owing to the hypoxic tumor microenvironment." (PMID 36541165, 2023). "Additionally, lithium modulated the polarization of macrophages to prevent the antitumor M1 polarization and promote the pro-tumor M2 polarization with a higher IFN-γ and lower IL-10." (PMID 36831437, 2023). "In HNSCC, tumor cells can recruit and drive macrophages to M2 phenotype by producing C–C chemokine ligand 2 (CCL2)/ CC chemokine receptor 2 (CCR2), IL-6, and IL-10." (PMID 37024932, 2023). "The secretion of immunosuppressive cytokines such as IL-10, IL-4, and TGF-β by B cells and Tregs, in addition to those produced by tumor cells, allows them to escape immune surveillance and leads to subsequent tumor progression and metastasis." (PMID 38139154, 2023). "Furthermore, regulatory T-cell-derived IL-10 mediates intratumoral CD8+ T-cell exhaustion and restrain anti-tumor immunity." (PMID 37151396, 2023). "We found that there was transcriptional upregulation of the gene ifng but not tnfb (also known as lymphotoxin-α) or il10 in the tumor tissues from mice receiving SRA-silenced DCs carrying the hsp110-gp100 vaccine." (PMID 36793731, 2023). "Moreover, we found that expression levels of IL10, TGFβ1 and FOXP3 in tumour B cells from untreated CLL B patients were predictive of disease progression." (PMID 36973425, 2023). "It is noteworthy, however, that expression of IL6 and IL10 was similar between tumor and adjacent normal tissue (data not shown)." (PMID 38375204, 2023). "Tumor cells or tissue-resident non-tumor cells can inhibit T cell function through the secretion of immunosuppressive factors, e.g., the cytokines IL-10 and TGF-β." (PMID 37511431, 2023). "Conversely, in tumors, after exposure to immunosuppressive cytokines IL-10 and TGF-β in the tumor microenvironment (TME), macrophages often differentiate into the M2 type, which is known to produce high concentrations of the immunosuppressive cytokine IL-10." (PMID 38258065, 2023). "It was shown that stimulation with tumor‐conditioned medium (TCM) prepared from glioma cells inhibited the induction of DC maturation by suppressing the expression of CD80, CD86, and IL‐12 p70, and promoting IL‐10 expression." (PMID 37088950, 2023).
tumor (continued). "Other factors such as IL-10 and TGF-β and cell surface changes such as the upregulation of PD-L1 may further inhibit tumor control by NK cells in GBM." (PMID 38137456, 2023). "Moreover, CAFs also release MMPs and IL-6, IL-10, TGF-β, C-C motif chemokine ligand 22 (CCL)-2, and CCL5, which stimulate tumor growth and block the natural immune response against cancer." (PMID 36831498, 2023). "In general, IL-10 is mainly produced by Th2, Th1, Treg, and Th17, and also by CD8+ T cells, monocytes, macrophages, DCs, B cells, mast cells, eosinophils, keratinocytes, epithelial cells, and even some tumor cells." (PMID 36835413, 2023). "IL-10 and TGFB induce tumor growth and alterations in the immune system, respectively." (PMID 37283734, 2023). "We observed that upon stimulation with tumor cells or tumor cells plus Obinutuzumab, the secretion of IFN-γ, Granzyme B, Perforin, Granulysin, and IL-10 was significantly increased in NK cells expressing hnCD16FR, whereas Granzyme A was secreted at high levels only in NK cells expressing hnCD16." (PMID 37316891, 2023). "If pDCs adopt the pro-tumourigenic phenotype, they can contribute to tumour growth, invasion, and/or angiogenesis stimulation by promoting the differentiation of naïve CD4+ T cells into T cells secreting IL-10, involving immunosuppressive functions, among others." (PMID 35406451, 2022). "Alternative macrophage activation via interleukin (IL)-4, IL-10, IL-13, transforming growth factor (TGF)-β, and colony-stimulating factor (CSF)-1 results in the tumor-supportive phenotype characterized by macrophage production of high amounts of anti-inflammatory cytokines such as IL-10 and TGF-β." (PMID 35784281, 2022). "Moreover, neoadjuvant chemotherapy increased the production of proinflammatory cytokines by tumor-infiltrating T cells, with enhanced TNF-α and IL-2 and reduced IL-4 and IL-10 expression." (PMID 36509285, 2022). "M2 GAMs further produce more Arg-1, TGF-β, IL-10, IL-6, and other abundant immunosuppressive cytokines, thus foster immunosuppression and pro-angiogenesis which contribute to growth and invasion of GBM after GBM tumor cells adapt to the pro-inflammatory TME." (PMID 35572545, 2022). "An important aspect of the mechanism of escape by the tumor from the immune system is the TME, which is characterized by a hypoxic state and is rich in inhibitory ligands and cytokines, such as IL-10 and TGF-β, which lead to tolerance by the immune cells towards the tumor." (PMID 36011024, 2022). "They demonstrated that microbial depletion using a combination of antibiotics and antifungals impacts the adaptive immune tumour response, increasing anti-tumour IFN-Y-producing cytotoxic T-cells and inhibiting the number of interleukin IL-17A and IL-10 producing pro-tumorigenic T cells." (PMID 35205769, 2022). "Breg cells-derived IL-10 can have a direct negative impact in T cell anti-tumour responses by disrupting the Th1/Th2 balance and inducing DCs to produce IL-4 and downregulate IL-12 and thus IFN-γ." (PMID 35406451, 2022). "Thus, CD73-specific siRNA-loaded NPs were able to decrease CD73 expression in tumor cells and inhibit adenosine production in the tumor site, which downregulated Treg and MDSC populations, as well as IL-10 secretion." (PMID 35335881, 2022). "Finally, we evaluated the immune regulation of PCSP-AuNPs using a mouse model with H22-tumor by testing the index of immune organs, splenic lymphocyte proliferation, cytokines levels (TNF-α and IL-10), and the CD4+/CD8+ cell ratio in the peripheral blood." (PMID 35762637, 2022). "MDSCs mainly inhibit T cell function by producing arginase I (Arg1), reactive oxygen species (ROS), and immunosuppressive cytokines such as IL-10 and TGFβ through activating STAT3, C/EBPβ, PI3K, and MAPK signaling pathways, which skews MDSCs into M2-like tumor-promoting phenotype." (PMID 35785030, 2022).
tumor (continued). "Moreover, M2 macrophages express immune-suppressive cytokines like IL-10 as well as transforming growth factor-beta (TGF-β), promote T regulatory (Treg) cell differentiation, and assist in tumor progression." (PMID 35419058, 2022). "The treatment may also trigger massive inflammatory and fibrotic reaction of the stroma orchestrated by cytokines including IL-1, IL-6, IL-10 and TGF-β, which can alter the tumor response to both radiation and chemotherapy." (PMID 36675979, 2022). "We show that infiltration of IgG4 + B cells correlate with intermediate but not high densities of B cell infiltration, IL-10 expression by tumor cells, and higher stage." (PMID 35255925, 2022). "This bsApt also induced an immune response (infiltration of CD3+ lymphocytes at tumor with increased expression of IFNγ, TNFα, and IL-10) and potentiated a combination of GVAX and transient Foxp3 blockade via the P60 peptide (resulting in decreased tumor size and increase survival) in vivo." (PMID 35141049, 2022). "The anti-tumor effect was related to a higher expression of TNF-α and IL-10 in the bladder." (PMID 35214691, 2022). "MRNA levels of CA12 exhibited positive correlations with those of HIF1A, TNF-A, IL-10, and IL-1B, but not those of IL-6, in tumor-derived monocytes." (PMID 35362480, 2022). "Moreover, upregulated expression of SCF protein increases secretion of IL-10 and TGF-β, resulting in the formation of an immunosuppressive tumor microenvironment and suppressed immune cell function." (PMID 35659268, 2022). "However, it also carries anti-tumor properties, as illustrated in murine knockout models and in human IL-10R deficiency analyses which found an increased propensity toward the development of malignancies including colon cancer and B cell lymphomas in the absence of IL-10/IL-10R signaling." (PMID 36031601, 2022). "This may be due to the fact that operational stress upregulates a number of immunosuppressive factors (e.g., VEGF, IL-10, TGF-β) that may facilitate establishment of metastatic niches in secondary organs and exacerbate tumor growth." (PMID 36230591, 2022). "On the other hand, M2 macrophages are part of the Th2 response, are induced by IL-4, produce IL-10 and TGF-β, and are related to an immunosuppressive microenvironment, which favors tumor cell growth, angiogenesis, matrix remodeling, and inhibition of adaptive immunity." (PMID 35055124, 2022). "In contrast, IL-19, a cytokine of the IL-10 super-family, was detected at higher levels in the supernatant of Δ/Δ Pdgfrb tumor cells, perhaps compensating for the lack of IL-10." (PMID 36045346, 2022). "Tumor-promoting cytokines IL-10 and IL-4, though elevated in the 6-hour sample, showed no significant changes during the burst phase." (PMID 35465347, 2022). "Prostaglandins and other lipid mediators of inflammation are produced quickly by the macrophages and then their actions are followed by those of cytokines such as IL-6 and interleukin-10 (IL-10) with the consequent activation of the EGFR signal, promoting the proliferation of tumor cells." (PMID 36432658, 2022). "Extensive research has shown that intestinal microbes stimulate the expression of chemokines such as TNF- α, IL-6, IL-10, and IL-1β or activate cytotoxic lymphocytes, such as CD4+ and CD8+ T cells or NK and NKT cells, in both peripheral blood and tumor to limit tumor growth." (PMID 36232344, 2022). "BJIKT treatment reduced the levels of TGF-β1 and IL-10, suggesting that BJIKT may reshape the immunosuppressive tumor microenvironment." (PMID 35873573, 2022). "ssGSEA analysis showed that L1CAM positively connected with cellular response to hypoxia, tumor proliferation signature, DNA repair, G2M checkpoint, MYC targets, TGFB, IL-10 anti-inflammatory signaling pathway, DNA replication, collagen production, and ECM degradation." (PMID 36212450, 2022).
tumor (continued). "IL-4, IL-6 and IL-10 are abundantly expressed in TME and play more pro-tumor role, while IL-2, IL-12, IL-15 and IL-18, which are immunomodulatory or pro-inflammatory factors, are restricted in the TME and play more anti-tumor role." (PMID 36698392, 2022). "Likewise, most ICD-related genes, including IL-6, IL-10, NLRP3, CD8A, CD8B, and TLR4, exhibited attenuated expression levels in tumor cells compared to normal cells." (PMID 36225939, 2022). "Furthermore, immune suppressive cytokines, such as IL-10 and TGF-β, are often secreted by tumor cells." (PMID 35185904, 2022). "Highly expressed p-STAT3 was positively correlated to high levels of IL-4, IL-6, and IL-10, and negatively correlated to low levels of IFN-γ in the serum, which may contribute to immune surveillance disability against tumor cells." (PMID 35530361, 2022). "INPP5A, HLA-G1, MMP-21, and IL-10 showed to be the most appropriate candidates to discriminate tumor/non-tumor groups due to the total AUCs of all combinations (>60%)." (PMID 36437782, 2022). "TAMs are in favor of GBM tumorigenesis because they do not support cytotoxic T cell activation and even inhibit their proliferation, as they secrete anti-inflammatory cytokines (e.g., IL-10 and TGF-β) and growth factors (e.g., EGF), thus promoting development and angiogenesis of the tumor." (PMID 35214076, 2022). "RCC cells may induce cytokine expression, such as IL-10 and TGF-β, in the tumor microenvironment (TME), leading to an immunosuppressive tumor state and promoting immune escape." (PMID 35372055, 2022). "These soluble factors like IL-6, IL-10, IDO, M-CSF, TGF-β1, PGE2, VEGF present in TME reprogram DCs to possess inefficient antigen-presenting capabilities, and an immunosuppressive regulatory phenotype that supports tumor progression." (PMID 36253762, 2022). "ICOS+ Tregs could produce a mass of IL‐10 and TGF‐β1,155 and the levels of tumor‐infiltrating ICOS+ Tregs were higher than those in tumor adjacent tissues in several cancers." (PMID 35474948, 2022). "CRC cells expressed anti-inflammatory cytokines such as IL-10 and TGF-β that could modulate the DC phenotype and supported tumor escape." (PMID 35619702, 2022). "Functionally, TAMs support MM proliferation (by secreting IL6), angiogenesis (by secreting VEGF, CCLs, matrix metalloproteinases (MMPs)), and immunosuppression (by secreting IL10, TGFβ, indoleamine 2,3-dioxygenase (IDO) and inhibiting IL12 and TNFα production) in the tumor microenvironment." (PMID 36421358, 2022). "Moreover, COX-2 inhibitors contribute to antitumor immunity by downregulating IL-10 and Tregs that modulate the systemic effect of PAFR-mediated tumor growth." (PMID 35603177, 2022). "On the contrary, activated DCs are converted into tolerogenic phenotypes in the tumour microenvironment, where they promote Tregs (and not T‐effector cells), with the production of TGFβ and IL‐10 as an escape mechanism from immune clearance." (PMID 35344301, 2022). "Our data suggest that serum IL-10 levels increase with tumor progression, whereas the level of TGF-β initially indicates that it inhibits epithelial growth, and the latter (day 40) appears to promote tumor progression." (PMID 36090972, 2022). "Moreover, western blot analysis showed decreased levels of the immunosuppressive cytokines IL-10 and TGF-β in M-HIFU generated tumor debris compared to untreated tumor tissue or T-HIFU." (PMID 36569907, 2022). "Five cytokines (IL-10, KC, LIF, MIP-2, and VEGF) involved in tumorigenesis, angiogenesis, and chemoattraction of immune cells were found to have significant positive correlations with tumor volume." (PMID 35681702, 2022). "In addition, IL-10 contributes to cancer progression by downregulating MHC class II expression in antigen-presenting cells and MHC class I expression in tumor cells, thereby creating an immune-permissive environment." (PMID 35615265, 2022).
tumor (continued). "Tumor immunosuppressive cells including M2 macrophages, MDSCs and Treg can multiply while effector CD4+ and CD8+ T lymphocytes are inhibited from doing so by IL-10 and TGF-β." (PMID 36439472, 2022). "To determine the mechanism of IL-10 secreted by TAMs to promote tumor cells mobility, we analyzed the phosphorylated proteins of tumor cells cultured in conditioned medium with or without IL-10 by human phospho-RTK array (R&D system)." (PMID 36038549, 2022). "In tumor-bearing animals, IL-27 downregulated the expression of FoxP3 in CD4+ and CD8+ T cells and prevented generation and expansion of Tregs, immunosuppressive T cells which inhibited antitumor immunity in IL-10- and TGF-β-dependent manner." (PMID 35757015, 2022). "Plasmodium infection could inhibit tumor secretion of Granulocyte-Macrophage Colony-Stimulating Factor human (GMCSF), IL-10, IL-6, C-C class chemokines (CCL)-17, and CCL-22 through the release of exosome-like vesicles." (PMID 36004920, 2022). "Hence, the IL-10 trap significantly inhibited tumor growth by decreasing M2 macrophages, MDSCs and TFG-β production in the tumor, and enhanced the median survival rate in the in vivo model." (PMID 35335881, 2022). "In cancer biology, it has been reported that GAS5 expression was negatively correlated with IL‐10 expression, and GAS5 may inhibit tumor growth by inhibiting IL‐10 secretion." (PMID 34936242, 2022). "Although not examined in the scope of this study, significant expression of IL-10 was also observed in TIB and may play a role in directing anti-tumor immune responses as well." (PMID 35255925, 2022). "Binding of TIGIT to CD155 (poliovirus receptor PVR) expressed on tumor cells results in the decreased secretion of pro-inflammatory cytokines such as IFN-γ, IL-17a, and TNF-α, and an increased secretion of the anti-inflammatory cytokine IL-10." (PMID 35345849, 2022). "Consequently, IL-23 induces Treg proliferation and promotes IL-10 and TGF-β expression, hence, suppressing tumor cell killing by cytotoxic lymphocytes." (PMID 36233088, 2022). "The effect of an IL-10 inhibitor regulated the PI3K/AKT signaling pathways to promote the antigen-specific CD8+ T cell responses and the alteration of the biological function of tumor-infiltrating macrophages." (PMID 35445137, 2022). "Additionally, by regulating the IL-10, COX-2, RAS/ERK, and PI3K/AKT pathways, CMV can promote the invasion of tumor cells." (PMID 36079151, 2022). "Accordingly, levels of the immunostimulatory cytokine IFN-γ significantly rose and immunosuppressive cytokines transforming growth factor β (TGF-β) and interleukin-10 (IL-10) significantly declined in tumor, suggesting that DEXP&A&N remodel tumor microenvironment." (PMID 35488312, 2022). "Thus, we determined tumor soluble factors that include angiogenic (VEGF), type 1 response (TNF-α, IFN-γ), type 2 response (IL-4, IL-5), and regulatory (IL-10) soluble factors." (PMID 36233245, 2022). "Furthermore, this study showed that HBV patients who developed HCC had increased expression of both IL-10 by TAMs and the exhaustion markers PD-1, CD152, and Lag-3 by tumor-infiltrating lymphocytes, as compared to non-tumor-infiltrating lymphocytes." (PMID 35454766, 2022). "Moreover, tumor targeted delivery of IL10-cetuximab fusion protein reduced apoptosis of intratumoral CD8+ T cells, boosted IFN-γ production and decreased tumor burden." (PMID 36248808, 2022). "TNF-α, IL-10, and IL-1β mimicked the effects of TSN in inducing the upregulation of CA12 expression in monocytes, and consistently, anti–TNF-α, anti–IL-10, and anti–IL-1β antibodies attenuated the induction of CA12 in tumor-exposed monocytes." (PMID 35362480, 2022). "We review some beneficial bacteria that act on DCs, NK cells, cytotoxic T cells, and helper T cells to promote the secretion of the pro-tumor cytokines IFN-1, IFN-γ, and IL-2 and down-regulate the secretion of TNF-α, IL-6, IL-10, and IL-22, thus exerting anti-tumor immune effects." (PMID 36438840, 2022).